TBX21 (T-box transcription factor 21)
Diseases named in the same sentence as TBX21 in open-access papers (continued):
Sharing a sentence is not in itself a finding about the gene and the disease.
VKH Syndrome (1 paper, 2015). "The frequencies of genotype and allele of 22 SNPs at TBX21, GATA3, Rorc genes didn't show a significant difference among BD patients, VKH syndrome patients and healthy controls." (PMID 25873156, 2015). "We applied the iPLEX system (Sequenom) and PCR-RFLP measurements to successfully evaluate 25 SNPs at TBX21, GATA3, Rorc and Foxp3 genes in an independent cohort containing 406 BD patients, 401 VKH syndrome patients and 613 healthy controls." (PMID 25873156, 2015). "The tested 25 SNPs in TBX21, GATA3, Rorc and Foxp3 did not associate with BD and VKH syndrome." (PMID 25873156, 2015).
tumor (105 papers, 2011 to 2026). "Co-culture experiments showed that TBX21-deficient tumor cells reduced the induction of CD25+Foxp3+ Treg cells from activated CD4+ T cells." (PMID 41573646, 2025). "Particularly, we reported new subtypes of tumor-associated CD8+ T cells characterized by different TBX21 and BHLHE40 activity, both of which are known regulators of CD8+ T cell functionality." (PMID 39907554, 2025). "TBX21 is associated with tumor progression and an immunosuppressive microenvironment in PCa, underscoring its potential role in modulating the tumor–immune balance." (PMID 41573646, 2025). "TBX21 knockdown was associated with reduced proliferation and increased apoptosis in vitro and suppressed tumor growth in vivo." (PMID 41573646, 2025). "Here again, we confirmed that the ileal mRNAs encoding Gata3, Bcl6, Rorc, and Tbx21 were increased in tumor bearers at day 10 of implantation compared to naive counterparts." (PMID 33262469, 2021). "Tamoxifen treatment also resulted in significantly decreased expression of immune genes implicated in Th1 differentiation and the cytotoxic anti-tumor response such as Ifng, Tbx21, and Gzmb." (PMID 30389925, 2018). "During a strong Th1 response, Tregs have been demonstrated to be able to differentiate into a subgroup of Tregs that express both forkhead box P3 (FoxP3) and T-box transcription factor TBX21 (T-bet), which are optimized to suppress the activity of Th1 cells, and are associated with tumor growth." (PMID 34439203, 2021). "In addition, HDAC8 expression was positively correlated with the genes encoding T‐cell exhaustion‐related genes, including TOX and DDIT3, and negatively correlated with the transcript genes encoding T‐cell activation‐related genes, such as TBX21, in multiple tumor types." (PMID 40013761, 2025). "Deletion of CHOP in CD8+ T cells resulted in the restoration of anti-tumor immunity by relieving the repression of T-bet (TBX21), a key regulator of type I anti-tumor immune responses." (PMID 41372991, 2025). "TBX21 is a transcriptional factor with critical functions in tumor development, roles of which in PCa were studied herein." (PMID 41573646, 2025). "It is shown by some studies that TBX21 exhibits tumor-suppressing effects in certain types of cancer, slowing down tumor progression by inhibiting cell proliferation and promoting apoptosis." (PMID 41573646, 2025). "This signature includes key genes for maintaining cellular cytotoxicity such as ZNF683,41PRF1, IL2RB, and IFNG and immune activation and exhaustion markers including LAG3, PDCD1, PRF1, and TBX21 that contribute to anti-tumor immunity." (PMID 41045934, 2025). "The combination of RKO-TBX21-shMYCT1 and LiCl was more effective in abolishing TBX21-mediated inhibition of tumor growth and volume than either treatment alone." (PMID 39744435, 2025). "MYC, TBX21 and BTN3A1 were found to be associated with the immune infiltration in the tumor tissues, especially related to the infiltration of T cells.As is well-known, a high infiltration of immune cells into tumors indicates better patient survival rates." (PMID 41343099, 2025). "T-box transcription factor 21 (TBX21) plays a vital role in regulating immune responses, systemic diseases, and tumor progression." (PMID 39744435, 2025). "The proportion of CD25+Foxp3+ Treg cells among activated CD4+ T cells was markedly reduced when co-cultured with TBX21-silenced tumor cells compared with sh-NC controls." (PMID 41573646, 2025). "In our cohort, T-bet protein was markedly increased in tumor tissues by IHC with quantitative scoring, and TBX21 mRNA was higher in tumors by qRT-PCR." (PMID 41573646, 2025). "In 4T1 tumor-bearing mice, calcitriol and tacalcitol significantly increased Rorc expression, while tacalcitol also increased Tbx21 expression." (PMID 40894304, 2025). "Levels of cytotoxic proteins, including STAT1, TNF-α, GZMB, and Perforin in tumor tissues were sharply enhanced by sh-TBX21 injection." (PMID 41573646, 2025).
tumor (continued). "In immune and tumor contexts, TBX21/T-bet is a canonical downstream target of interferon-γ–STAT1 signaling and helps imprint Th1-like programs." (PMID 41573646, 2025). "To verify that TBX21 knockdown occurred specifically within tumor epithelial cells, we performed double immunofluorescence staining for TBX21 with EpCAM (tumor epithelial marker) and CD3 (T-cell marker)." (PMID 41573646, 2025). "Analyzing by tissue distribution, the gene expression levels of ZEB2 and TBX21 as well as ZEB2 transcriptional activity were downregulated in the tumor environment relative to the adjacent normal tissue and peripheral blood." (PMID 41203628, 2025). "We found that CRC liver metastatic samples exhibited lower TBX21 expression than primary tumor tissues." (PMID 39744435, 2025). "Collectively, these results highlight the important role of TBX21 in regulating tumor cell migration." (PMID 39744435, 2025). "Subsequently, IHC staining and RT-PCR of TBX21 in normal and tumor tissues was conducted for validation." (PMID 41573646, 2025). "Expressions of Cd8, Tbx21 and Granzyme B in tumor tissues of ACY-1215 monotherapy group and anti-PD1 monotherapy group were higher than those of control group." (PMID 38231305, 2024). "Tumor tissues of mice were taken and made into pathological sections, and the functional biomarkers that can reflect T cell activation, such as Cd8, Tbx21 and Granzyme B, were detected by immunohistochemistry." (PMID 38231305, 2024). "Mechanistically, it has been demonstrated that upregulation of DDIT3 blunts tbx21 transcription in tumor-infiltrating CD8+ T cells, impairing T-cell effector immunity and indicating regulation of their antitumor activity." (PMID 38474084, 2024). "Further, the genetic deletion of the transcription factor T-bet (Tbx21) blocked the increased IFN-γ expression on all subsets while ablating the therapeutic benefits of SC79 on tumor growth." (PMID 36323740, 2022). "All samples (except C215), which showed the increase of the TBX21/GATA3 ratio after the co-culture with tumor cells, revealed the increase of the anti-tumor reactivity." (PMID 35606862, 2022). "To further evaluate the impact of TBX21 on survival and anti-tumor immunity, we looked at other indicators of immune resistance." (PMID 36230517, 2022). "B-cell-derived neoplasms are found to express the TBX21 gene, which encodes for T-bet protein and seems to have an important role in the oncogenesis of this category of hematological diseases." (PMID 35955786, 2022). "Within the tumor-infiltrating CD4_4 cluster, we observed increased expression of the Th1 driver TBX21 (T-bet), activation marker LAG3 and NR4A2 and cytokine expression." (PMID 33504936, 2021). "CD4-Th1-like cells expressing high levels of Tbx21, Gzmb, and Ifng had been shown to have anti-tumor capability through activating monocytes and responding to interferon-γ46." (PMID 32709844, 2020). "Calcitriol or its analogues downregulated the expression of 4 genes related to the Th1 response in tumour tissue (Ifng (only calcitriol), Socs1, Tbx21 and Fasl) and upregulated 5 genes related to the Th2 response (Ccl11, Ptgdr2, Il9, Asb2 and Il5)." (PMID 31595196, 2019). "By using TAK-242 before co-injection with PC, tumor engraftment significantly decreased with an up-regulation of TBX21 and INFγ and a consequent Th1 response." (PMID 31541083, 2019). "In agreement, ectopic expression of TBX21 raised remarkably the proportion of SP cells (P < 0.0001) and enhanced ability dramatically in the tumor sphere formation of A549 cells (P < 0.0001)." (PMID 29615105, 2018). "To further identify the role of TBX21 in regulating cancer stemness in vivo, we performed tumor xenograft studies in NOD/SCID mice injected with either A549-shTBX21 or A549-sc cells." (PMID 29615105, 2018). "We next analyzed the mRNA expression of the hallmark transcription factors for Tc1 (TBX21) and Tc2 (GATA3) in sorted CD8+ T cells from PBMC, SN, and tumor." (PMID 29966014, 2018).
tumor (continued). "Then we investigated the potential biological function of TBX21 in disease progression with biological experiment and confirmed that TBX21 promoted the cancer stemness of tumor cells to reduce the survival time of patients with LUAD." (PMID 29615105, 2018). "Furthermore, percentages of TNF-α+CD8+ Tand GZMB+CD8+ T cells in tumor tissues were notably increased by sh-TBX21, indicating a shift toward a more active antitumor immune microenvironment." (PMID 41573646, 2025). "Moreover, by silencing TBX21, the in vitro and in vivo growth of PCa cells were dramatically repressed, along with enhanced apoptosis in tumor cells, implying that TBX21 functioned as an oncogene in PCa." (PMID 41573646, 2025). "(a) The consensus trajectory of tumor-associated CD8+ T cells in non-small cell lung cancer (NSCLC) identified CD8-ZNF683-T1 and CD8-ZNF683-T2 as two subtypes of CD8-ZNF683, which are influenced by TBX21." (PMID 39907554, 2025). "Finally, the precise mechanism by which tumor cell–derived TBX21 influences T-cell differentiation and function remains to be elucidated and will be explored in subsequent investigations." (PMID 41573646, 2025). "Recent findings also highlight a critical role for TBX21 in tumor progression." (PMID 39744435, 2025). "Moreover, TUNEL-stained tumor cells were sharply increased in tumor tissues by the injection of sh-TBX21, accompanied by downregulated Ki67 and TBX21." (PMID 41573646, 2025). "The RNAseq results provided additional support of the CD8 and granzyme B IHC data and suggested that Th1 response might be enhanced in the post-treatment tumor microenvironment due to up-regulation of IFNg and TBX21 gene expression." (PMID 39965362, 2025). "Moreover, anti-inflammatory factors, including TGF-β, IL-10, IL-13, and Arg1 in tumor tissues were notably downregulated by sh-TBX21 injection." (PMID 41573646, 2025). "The tumor volume and tumor weight were sharply repressed by sh-TBX21." (PMID 41573646, 2025). "Tumor samples exhibited lower TBX21 expression compared to normal tissues." (PMID 39744435, 2025). "We found that Microarray data TBX21 levels were sharply boosted in PCa tumor tissues." (PMID 41573646, 2025). "To further reveal the mechanisms underlying the helper functions of NK cells in CD8+ T cell‐dependent anti‐PD‐L1 immunotherapy, we set out to determine tumor growth after anti‐PD‐L1 immunotherapy in mice with NK cell‐specific deletion of Prf1, Ifng, Tbx21, or Eomes." (PMID 36807566, 2023). "However, this study expressed TBX21 in Trm cells, which not only play a role in initial tumour immunity but also have a strong influence on other immune cells, such as Th1 cells, due to IFN-γ expression." (PMID 36869093, 2023). "In addition, the activity of TFs such as EOMES and TBX21 were higher in immune cells than in tumor cells, which is consistent with the role of these TFs in driving lymphocyte differentiation." (PMID 36155797, 2022). "In addition, TBX21 expression in T cells was demonstrated in mouse experiments to control tumor progression and antimetastasis." (PMID 36620585, 2022). "Moreover, previous studies have suggested that TBX21 is an important transcriptional regulator of tumor-reactive CD8T-cells, which are critical for response and survival." (PMID 36230517, 2022). "Conversely, treatment of male LR/Stat3Δ/Δ mice with anti-IL-6 antibody resulted in significantly increased expression levels of immune markers indicative of M1 macrophage polarization, Th1 differentiation and/or cytotoxic (CD8 T/NK cell) anti-tumor response (Ifng, Tbx21, and Gzmb)." (PMID 30389925, 2018). "Furthermore, the study showed that TBX21 activation transduced a TBX21–IL-4 signaling cascade to promote tumor initiation, tumor growth and expression of stemness markers." (PMID 29615105, 2018). "However, in the tumor setting, Eomes tends to be co-expressed with T-bet in exhausted CD8+ T cells, although overexpression of Eomes down-regulated Tbx21 transcripts that encode T-bet." (PMID 30619337, 2018).
tumor (continued). "We did not observe a significant association with the Th1 marker TBX21, which is supposed to be critical for an tumour suppressing immune response." (PMID 25889974, 2015). "Herein, in tumor-bearing mice, the proportion of Th17 cells was markedly enriched by silencing TBX21, while the proportion of Treg cells was dramatically repressed by silencing TBX21, implying that TBX21 might enhanced the immunosuppressive function in PCa." (PMID 41573646, 2025). "Employing Tbx21-floxed (Tbx21fl/fl) mice to Gzmb-Cre mice to create Tbx21fl/fl;Gzmb-Cre (Tbx21−/−) mice, Tbx21 knockout significantly suppressed the proportion of lung tumor-reactive Teff cells in the spleen on day 7 post-tumor cell inoculation in both KP.SIY models." (PMID 41203628, 2025). "The dysfunction of the anergic NK population was reflected by the reduced TL of Eomes and Tbx21, which are TFs known to play a role in the maturation of NK cells, suggesting compromised maturation and reduced ability of the anergic population to control tumor growth or infections." (PMID 38637625, 2024). "Furthermore, the variant frequencies in the tumor of five mutations within the OXTR, TBX21, CSPP1, and PTPN21 genes ranged from 40%–50% in the primary tumor, thus suggesting the likelihood that these were present in virtually all tumor cells at the onset (heterozygosity)." (PMID 26527318, 2016). "Moreover, in conformity with Xiong’s report, the proportion of Treg cells in activated CD4+ T cells was sharply reduced by sh-TBX21-transfected PCa cells, indicating that TBX21 might limit the anti-tumor property of CD8+ T cells via enhancing the proportion of Treg cells." (PMID 41573646, 2025). "However, in other types of cancer, TBX21 may promote tumor growth and metastasis." (PMID 41573646, 2025). "F. nucleatum inhibits the expression of PD‐1 in CD8+ TILs by synthesizing butyrate and epigenetically activating the TBX21 transcription factor, thereby increasing cytotoxicity of CD8+ TILs and tumor cell killing." (PMID 40530896, 2025). "Tc1 is a subtype of CT8+ T with tumor-killing function, regulated by transcription factors EOMES and TBX21." (PMID 39076970, 2024). "Genes such as ADGRG1, TBX21, S1PR5, FCRL6, and FCGR3A showed relatively selective expression in tumor-reactive T cells (the average expression in bystander T cells < 0.5)." (PMID 39243082, 2024). "The transcriptional programs regulated by TBX21, ZNF595, FOSL2, ZNF83, ZNF484, IKZF2, and ELK3 were found to be significantly activated in tumor-reactive T cells." (PMID 39243082, 2024). "high PLP2+ Tumor EPCs score group highly expressed ATF6, ELF1, ERG and PLAGL1 genes, while low PLP2+ Tumor EPCs score group highly expressed ATF5, TBX21, SPIB, LHX2 and JUND genes." (PMID 38482016, 2024). "Selected genes are reflecting main anti-tumor immune pathways, such as Th1 signaling (IFNG, TBX21, CD8A/B, IL12B, STAT1 and IRF1), Th1 chemoattraction (CXCL9, CXCL10 and CCL5) and cytotoxic functions (GNLY, PRF1, GZMA, GZMB and GZMH)." (PMID 37726776, 2023). "CB2 stimulation reduces the expression of CD9, SEC61G, TBX21, and TMSB4X genes involved in tumor growth and progression, and also negatively affects downstream intracellular pathways." (PMID 35955786, 2022). "There is significant research linking TBX21 with T cell exhaustion; therefore, it fits that this gene would impact survival in the subset of CRC patients characterized by an active anti-tumor immune response." (PMID 36230517, 2022). "In contrast, co-culturing MyLa cells with MF tumor-derived fibroblasts significantly suppresses the expression of IFNG (p < 0.0002) and TBX21 (p < 0.0004) in MyLa cells." (PMID 33941102, 2021). "Analysis of specific genes involved in CD4+ differentiation and function revealed differential methylation status of TBX21, GATA3, RORC, FOXP3, IL10 and IFNG in tumor CD4+ T-cells." (PMID 34012510, 2021).